KISS1R (KISS1 receptor)
Diseases named in the same sentence as KISS1R in open-access papers (continued):
Sharing a sentence is not in itself a finding about the gene and the disease.
breast carcinoma (continued). "More recent studies highlighted the positive correlation of KISS1/KISS1R system with breast cancer progression and patient prognosis." (PMID 27101408, 2016). "Initial in vitro and in vivo screens using the KISS1R-expressing breast cancer cell line MCF-7 revealed strong binding of the kisspeptin probe, validating its potential as a KISS1R marker." (PMID 27158817, 2016). "In breast cancer, however, KP/KISS1R has been found to play a diametric role." (PMID 38256878, 2023). "Overall, a theory has been proposed that the subtype of breast cancer may determine the effects kisspeptin and KISS1R have on metastasis." (PMID 35955878, 2022). "Furthermore, in vitro studies have also resulted in contrasting conclusions regarding kisspeptin and KISS1R function in breast cancer, with some suggesting they act in a pro-metastatic manner while others suggest they act in an anti-metastatic manner." (PMID 35955878, 2022). "Indeed, it has been demonstrated that in several breast cancer cell lines the anti-proliferative effects observed after kisspeptin stimulation is dependent on exogenous overexpression of the receptor KISS1R." (PMID 35955878, 2022). "This may, in part, account for switching from the metastasis suppressor to metastasis promoter roles of the KISS1/KISS1R system in breast cancer." (PMID 30123188, 2018). "Based on the use of established cell models of breast cancer and breast cancer patient data, several studies from our laboratories, and those of others would later show that KISS1 and its receptor KISS1R, in striking contrast to most cancers, promote breast cancer invasion, and metastasis." (PMID 30123188, 2018). "KISS1R has been implicated in promoting breast cancer metastasis in vivo, and kisspeptin-10 (KP-10) mediated activation of KISS1R has been shown to stimulate TNBC MDA-MB-231 and Hs578T cell invasion; these cells express endogenous KISS1R." (PMID 30046386, 2018). "KISS1R expression has been identified as a driver of metastasis in breast cancer cells." (PMID 27015368, 2016). "Recently, a pro-invasive role has been proposed for KISS1R in breast cancer." (PMID 24979721, 2014). "Also, the KISS1 receptor was recently shown to promote breast cancer due to overexpression." (PMID 29861840, 2018). "We used human MDA-MB-231 and SKBR3 breast cancer cell lines as positive controls to analyze KISS1 and KISS1R protein levels." (PMID 39404414, 2024). "Furthermore, a potential role of the KiSS-1/KiSS-1R complex has been proposed in the early stage of breast cancer development so this complex is not only involved in the advanced stages of the tumor, but could also represent a good target to hit tumors at an initial and final stage of development." (PMID 29760678, 2018). "To date, in addition to playing a promoter role in breast cancer metastasis, KISS1 and KISS1R also appear to promote hepatic cell carcinoma." (PMID 30123188, 2018). "Taken together, this data suggests that KISS1, KISS1R and AXL are upregulated in invasive breast cancer cells (Hs578T, MDA-MB-231, SKBR3FLAG-KISS1R), compared to non or weakly invasive breast cancer cells (SKBR3, MCF7 and T47D)." (PMID 28422142, 2017). "In support of these observations in breast cancer, treatment of ERα-positive breast cells with tamoxifen (an ER antagonist commonly used as an anti-cancer drug), increased KISS1 and KISS1R mRNA levels." (PMID 28422142, 2017). "Particularly in estrogen receptor-alpha (ERα)-negative breast cancer, the KISS1R activation has been reported to increase cell migration and invasiveness, and thus ERα appears to negatively regulate KISS1R-mediated cell invasion." (PMID 38256878, 2023). "Despite its clear anti-metastatic effects in many cancers, in breast cancer, the role of kisspeptin/KISS1R is still not clearly understood." (PMID 35955878, 2022). "Taken together, these data suggest a role for KISS1R in regulating glutamine metabolism pathway in ERα-negative breast cancer cells." (PMID 32034133, 2020).
breast carcinoma (continued). "Next, to investigate if KISS1R activation promotes fibulin-3 expression, ERα-negative breast cancer cells were treated with 100 nM KP-10 and fibulin-3 protein expression in cell lysates, and in conditioned media was examined by western blot analysis." (PMID 30046386, 2018). "We have previously shown that ERα-negative SKBR3 breast cancer cells express low levels of endogenous KISS1R, and stable over-expression of FLAG-KISS1R promoted an EMT-like event, resulting in increased tumor cell invasion." (PMID 30046386, 2018). "We previously showed that KISS1R expression triggered AXL expression in the ERα-negative cells SKBR3 breast cancer cells, which normally do not express AXL." (PMID 28422142, 2017). "Previous work has shown that KISS1 and KISS1R levels are upregulated in invasive ERα-negative breast cancer cells (e.g., MDA-MB-231, Hs578T, SKBR3FLAG-KISS1R) in contrast to weakly invasive, ERα-positive luminal breast cancer cells (T47D, MCF7) or ERα-negative luminal SKBR3 cells." (PMID 32034133, 2020). "Finally, we also reported that in chick embryo assays, ERα-negative SKBR3 breast cancer cells expressing exogenous KISS1R exhibited increased invasion." (PMID 30123188, 2018). "This study showed that treatment of ERα-positive MCF7 and T47D breast cancer cells with tamoxifen, a selective estrogen receptor modulator (with antagonistic role in breast tissue), stimulated KISS1/KISS1R expression, implicating that ERα signaling downregulates KISS/KISS1R levels." (PMID 30123188, 2018). "Our results suggest that placental factors may reduce breast cancer progression depending on ER status of cancerous cells and support the concept that it is the ER status of mammary cells that dictates whether or not KISS1R may be a novel clinical target for treating breast cancer metastasis." (PMID 27101408, 2016). "Furthermore, we found that the TNBC cell lines (MDA-MB-231 and Hs578T) which endogenously express KISS1R also robustly express AXL, but the ERα-positive breast cancer cells (T47D and MCF7), that barely express KISS1R, do not express AXL." (PMID 28422142, 2017).
melanoma (14 papers, 2008 to 2025). A malignant, usually aggressive tumor composed of atypical, neoplastic melanocytes. "The Kiss1 gene that encodes the kisspeptin precursor, Kiss1, was discovered in 1996 as a metastasis suppressor in melanoma cell lines, and a few years later, Kiss1R, previously known as GPR54, was discovered." (PMID 34576283, 2021). "Kisspeptin is a peptide encoded by the metastasis suppressor gene kiSS-1 for melanoma cells, isolated from human placenta and acting as endogenous ligand of the orphan G protein-coupled receptor 54 (GPR54, now named kisspeptin receptor, kiSS-1R)." (PMID 30477219, 2018). "Besides its role as a metastasis suppressor, first revealed in a melanoma model using SSH approach, kisspeptin/metastin and its receptor GPR54/KISS1R were recently implicated as important triggers of the complex process of sexual maturation." (PMID 18211678, 2008). "KISS-1, an antimetastatic gene first identified in melanoma, acts biologically by binding to G protein-coupled receptor, also known as KISS-1 receptor (KISS-1R)." (PMID 37024487, 2023). "The original discovery of differential expression of KISS1R in metastatic and nonmetastatic melanoma cell lines sparked extensive studies on the bio‐oncology of KP and KISS1R in numerous cancers that reported a diversity of effects; many of which were contradictory." (PMID 39775975, 2025). "Pairs of melanoma cell lines sensitive and resistant to PLX4032, displaying different levels of KiSS1 and KiSS1R as well as a different pattern of KiSS1 release upon PL4032 exposure were considered to study whether the response to antitumor agents can be improved by the combination with KP54." (PMID 37790750, 2023).
Obesity (14 papers, 2016 to 2025). Accumulation of substantial excess body fat. "Both male and female kisspeptin receptor (Kiss1r) knockout mice develop obesity when housed at 22 °C, but at thermoneutral conditions (30 °C), the obese phenotype was attenuated in female mice only." (PMID 40702736, 2025). "Using a mouse model of MASLD, we found that enhancing KISS1R activation by administering a long-acting kisspeptin analog, KPA, decreases the synthesis of numerous lipid species shown to be linked to obesity, type 2 diabetes, and steatosis, in addition to HCC." (PMID 40862768, 2025). "In summary, this study reveals that KISS1R signaling inhibits hepatic DNL, reducing the production of FFA linked to obesity, steatosis, and HCC." (PMID 40862768, 2025). "In nonalcoholic fatty liver disease, that correlates with a rise in obesity and T2D, activation of the Kiss1r signaling pathway had therapeutic effects in HFD‐fed C57BL/6J mice." (PMID 38599822, 2024). "These phenotypes suggest that, under pathophysiological conditions such as obesity and insulin resistance, hepatic KISS1R plays a crucial role in suppressing the development of the NAFLD phenotype by reducing hepatic lipogenesis." (PMID 35349482, 2022). "Inactivation of kiss1r in mice results in obesity and diabetic phenotype, and kisspeptin and its receptor are expressed in metabolic tissues (e.g., fat, liver and pancreatic tissues) and likely plays a role in regulating insulin secretion." (PMID 34300220, 2021). "Thus, it was confirmed that the previously observed obesity and decreased metabolism in global Kiss1r KOs reflect impaired KP signaling in non‐BAT tissues." (PMID 38599822, 2024). "Impaired Kiss1/Kiss1r signalling leads to spontaneous development of obesity in adult female mice, with greater body weight, higher abdominal adiposity, reduced glucose tolerance, diminished thermogenic capacity within brown adipose tissue and a lower core body temperature." (PMID 37732890, 2023). "In rats fed a high-fat diet, there was a reduction in Kiss1 expression within WAT, suggesting that diet-induced obesity may disrupt Kiss1/Kiss1r signalling." (PMID 37732890, 2023). "Finally, Kiss1R knockout results in impaired glucose tolerance and obesity in adult female mice, while kisspeptin administration may reduce food intake in rodents." (PMID 27990162, 2016). "As Kiss1r is expressed in BAT, KO studies by Tolson et al106 explored the role of this expression in relation to obesity." (PMID 38599822, 2024).
central precocious puberty (13 papers, 2011 to 2024). "By contrast, mutations which cause KISS1R hyperactive in humans result in central precocious puberty (CPP)." (PMID 35837314, 2022). "Patients with central precocious puberty revealed a gain-of-function mutation in the C terminal tail of KISS1R (R386P)." (PMID 34646652, 2021). "Conversely, activating mutations of KISS1R in humans caused central precocious puberty." (PMID 36262016, 2022). "Mutations in the KISS1 gene or disorders of the kisspeptin/KISS1R system may lead to clinical symptoms such as idiopathic hypogonadotropic hypogonadism (iHH), central precocious puberty (CPP) and female infertility." (PMID 35837314, 2022). "In addition, two KISS1R mutations (P74S and H90D) were recently identified with idiopathic central precocious puberty." (PMID 34646652, 2021). "Brain tumors, brain trauma and gene mutations, such as KISS1 and KISS1R mutations, are known to cause central precocious puberty (CPP)." (PMID 28546864, 2017). "However, until now only the kisspeptin system KISS1/KISS1R, MKRN3, and DLK1 or Pref-1 identified in sporadic or familial central precocious puberty cases have been confirmed causal variants leading to CPP." (PMID 34748517, 2021). "Conversely, activating variants in KISS1R and KISS1 caused central precocious puberty (CPP)." (PMID 37272254, 2023).
hypogonadism (13 papers, 2011 to 2025). A disorder characterized by decreased function of the gonads. "Therefore, mild to severe restricted sexual transformation to hypogonadism can occur due to mutations in GPR54/KISS1R." (PMID 34646652, 2021). "Kiss1r KO mice were studied as model of persistent hypogonadotropism and anovulation." (PMID 26642206, 2015). "However, the crucial role of kisspeptin was discovered through the discovery of humans with Kiss1r mutations exhibiting abnormal LH pulses and hypogonadism, and Kiss1r KO mice having an absence of LH secretion, which could be rescued by returning Kiss1r expression in GnRH neurons." (PMID 40539639, 2025). "In our study, we used Kiss1r KO mice as model for sustained (but not complete) hypogonadotropism." (PMID 26642206, 2015).
breast tumors (7 papers, 2011 to 2020). "This study also demonstrated that KISS1/KISS1R signaling occurs in an autocrine manner in breast epithelial cells to promote in breast tumor development in an animal model." (PMID 30123188, 2018). "In other cancer types, several studies demonstrate that kisspeptin may act as a tumor suppressor, while a handful of recent studies suggest that Kiss1R activation may promote breast tumor proliferation and metastasis." (PMID 30777054, 2019). "Breast tumors are divided into estrogen receptor α (ERα)-positive and ERα-negative tumors and the role of KiSS-1 and KiSS-1R in the positive group are conflicting." (PMID 29760678, 2018). "In contrast, Jarzabek and colleagues demonstrated that ERα-positive breast tumors express higher levels of both KiSS-1 and KiSS-1R than ERα-negative tumors." (PMID 29760678, 2018). "So far, it is not possible to assign a clear role to KiSS-1/KiSS-1R system in regulating the progression of ERα-positive and ERα-negative breast tumors as the complex cross-talk between KiSS-1 expression and signaling pathways regulated by ERα deserve further investigation." (PMID 29760678, 2018).
polycystic ovary syndrome (7 papers, 2019 to 2025). A disorder that manifests as multiple cysts on the ovaries. "The aim of this study was to investigate the expression of anti-Mullerian hormone (AMH), kisspeptin 1 (KISS-1), and kisspeptin 1 receptor (KISS1r) in rat models of polycystic ovary syndrome (PCOS) and controlled ovarian stimulation (COS)." (PMID 31782699, 2020). "Second, the potential mechanism behind the observed effect on increased body weight, polycystic ovaries, impaired estrous cycle and endocrine aberration involved altering GABA, glutamate, kisspeptin/kiss1r and NKB/NK3r in the hypothalamic pituitary region." (PMID 32921318, 2020).
Kallmann syndrome (6 papers, 2011 to 2020). Kallmann syndrome (KS) is a developmental genetic disorder characterized by the association of congenital hypogonadotropic hypogonadism (CHH) due to gonadotropin-releasing hormone (GnRH) deficiency, and anosmia or hyposmia (with hypoplasia or aplasia of the olfactory bulbs). "As an example, for Kallmann syndrome (ORPHA:478), an endocrine disorder caused by mutations in gene Kiss1r that affects both males and females but is diagnosed more frequently in human males, we observed that male models more closely matched the disease profile." (PMID 31986132, 2020). "Several genes were reported only in syndromic cases; CHD7 (CHARGE syndrome), CR1 (van der Woude syndrome), EFNB1 (craniofrontonasal syndrome), KISS1R (Kallmann syndrome), MID1 (Opitz G/BBB syndrome), REN (van der Woude syndrome), and SOX9 (Pierre-Robin syndrome)." (PMID 31122291, 2019). "Although a single evidence is not enough to draw any conclusion, the relation of the KISS1R mutation with Kallmann syndrome including the co-occurrence of OFC and TA is worth to be further investigated." (PMID 27699475, 2016). "Here, we identified one heterozygous KISS1R mutation in a KS patient with IHH, anosmia, lack of bilateral olfactory bulbs, cleft lip, and dental agenesis." (PMID 26199944, 2015).
prostate carcinoma (6 papers, 2016 to 2025). A carcinoma that arises from epithelial cells of the prostate gland. "Additionally, our data suggests that KISS1R may be linked to Gq to initiate intracellular calcium mobilization in at least some compromised prostate cancer cells." (PMID 27015368, 2016). "Another study showed that KISS1R signaling induced the activation of eukaryotic translation initiation factor 2α kinase 2 (EIF2AK2) in prostate cancers and thereby inhibited cell growth and metastasis." (PMID 30123188, 2018). "Hence, the therapeutic potential of KISS1R agonists in treating men with prostate cancer has recently been investigated." (PMID 27015368, 2016). "Thus, to establish if KISS1R expression can influence sensitivity to kisspeptin in prostate cancer, we performed fluorescence based calcium mobilization assays in control (shSCX) and shRb LNCaP and 22Rv1 cells after normoxia or hypoxia treatments." (PMID 27015368, 2016). "Our observed increases in KISS1R expression in both LNCaP and 22Rv1 cells after Rb-loss and hypoxia were surprising as a previous report suggested that KISS1 inhibits metastasis and that both KISS1 and KISS1R protein levels appear to decrease with prostate cancer progression." (PMID 27015368, 2016). "The finding is reminiscent of that seen in prostate cancer where at the cellular level while KISS1 and KISS1R expression correlated with the disease, serum kisspeptin did not." (PMID 30123188, 2018).
steatosis (6 papers, 2018 to 2025). Increased lipid within the cytoplasm of cells. "Whereas in these animals, a deletion of hepatic Kiss1r exacerbated hepatic steatosis, whereas stimulation of Kiss1r offered protection against steatosis and decreased fibrosis." (PMID 38599822, 2024). "On the contrary, activation of hepatic KISS1R plays a protective role against steatosis and reduces fibrosis of the liver in a diet-induced mouse model of non-alcoholic liver disease." (PMID 37968564, 2023). "Taken together, the increase in liver TGs in the LKO HFD-fed mice suggests that hepatic KISS1R plays a protective function against steatosis." (PMID 35349482, 2022). "Since our data revealed that KISS1R signaling inhibits steatosis in vivo, a direct effect of KP on hepatic lipogenesis was examined using isolated primary hepatocytes; we observed that they expressed KISS1 in a punctate pattern typical of secreted peptides." (PMID 35349482, 2022). "In contrast, enhanced stimulation of KISS1R protected against steatosis in wild-type C57BL/6J mice and decreased fibrosis using a diet-induced mouse model of NASH." (PMID 35349482, 2022). "We also investigated the impact of overexpressing hepatic Kiss1r on steatosis." (PMID 40862768, 2025). "KISS1R agonist fails to protect against steatosis and NASH progression in a hepatic Kiss1r-deficient mouse model." (PMID 35349482, 2022). "Next, we tested whether increased expression of hepatic Kiss1r is sufficient to improve steatosis." (PMID 40862768, 2025). "Plasma kisspeptin levels are also increased in patients with steatosis and MASH, compared to healthy subjects, suggesting that the upregulation of the KISS1R signaling pathway is a compensatory and protective response aiming to resolve MASH." (PMID 39404414, 2024). "This provided “on-target” confirmation that the protective effect on steatosis and NASH progression is due to direct hepatic Kiss1r signaling by regulating these key metabolic pathways." (PMID 35349482, 2022). "KISS1R agonist fails to protect against steatosis and NASH progression in hepatic AMPK-depleted mice." (PMID 35349482, 2022).